NBPF3 (NBPF member 3)
Synonyms: AE2
Tractability: PROTAC: ubiquitination databases record sites on it.
Gene: Protein-coding gene on chromosome 1 (21,440,099 to 21,485,005, forward strand). Ensembl gene ENSG00000142794.
Subcellular location: Cytoplasm
Subcellular location (Human Protein Atlas): Cytosol; Nucleoplasm; Nuclear speckles
Gene Ontology:
Cellular component: cytoplasm
Genetic constraint (gnomAD): Loss-of-function variants: 52 observed, 57.69 expected, observed/expected ratio (o/e) 0.9, 90% interval 0.72 to 1.14. The upper end of that interval is the gene's LOEUF score, 1.14, which puts it in group 4 of 6, group 1 being the genes least tolerant of losing a copy. Missense variants: 445 observed, 522.54 expected, observed/expected ratio (o/e) 0.85, 90% interval 0.79 to 0.92. Synonymous variants: 155 observed, 193.35 expected, observed/expected ratio (o/e) 0.8, 90% interval 0.7 to 0.92.
Homologues: Orthologues: chimpanzee NBPF3 (97% identical). Paralogues in human: NBPF26 (76% identical), NBPF20 (74% identical), NBPF12 (74% identical), NBPF10 (73% identical), NBPF14 (73% identical), NBPF19 (73% identical), NBPF8 (73% identical), NBPF9 (73% identical), NBPF15 (69% identical), NBPF1 (63% identical), NBPF11 (61% identical), NBPF4 (45% identical), and 1 more.
Diseases named in the same sentence as NBPF3 in open-access papers:
NBPF3 is named in the same sentence as 6 diseases in open-access papers, as found by Europe PMC text mining. Sharing a sentence is not in itself a finding about the gene and the disease. The quoted sentences say what the papers report.
neuroblastoma (2 papers, 2013 to 2025). Neuroblastoma (NB) is the most common solid, extracranial childhood tumor. "NBPF3 (Neuroblastoma Breakpoint Family Member 3) is a member of the neuroblastoma breakpoint family, which consists of dozens of recently duplicated genes primarily located in segmental duplications on human chromosome 1." (PMID 41158885, 2025). "For example, the Dizeez-generated and manually-validated associations between SOX8 and mental retardation and between NBPF3 and Neuroblastoma are not present in the DGA." (PMID 23951102, 2013).
Obesity (2 papers, 2020 to 2025). Accumulation of substantial excess body fat. "Furthermore, numerous studies have identified the epigenetic modifications on various robust genes like the FTO, NBPF3, and SREBF1 were related to obesity, suggesting the regulatory role of genetic factors in obesity-associated methylation changes." (PMID 40702573, 2025). "In order to investigate the strong association of the obesity-associated (FTO) gene variants and obesity with epigenetic changes, a genome-wide methylation scan in obese and normal weight females identified 20 DM sites in obese females, of which one was hypomethylated site in NBPF3 gene." (PMID 32605309, 2020).
NBPF3 also shares sentences with these, for which no sentence is quoted: Diamond-Blackfan anemia (1 paper); mental retardation (1); microcephaly (1); schizophrenia (1).